ADARB1 (adenosine deaminase RNA specific B1)
Description:
Catalyzes the hydrolytic deamination of adenosine to inosine in double-stranded RNA (dsRNA) referred to as A-to-I RNA editing. This may affect gene expression and function in a number of ways that include mRNA translation by changing codons and hence the amino acid sequence of proteins; pre-mRNA splicing by altering splice site recognition sequences; RNA stability by changing sequences involved in nuclease recognition; genetic stability in the case of RNA virus genomes by changing sequences during viral RNA replication; and RNA structure-dependent activities such as microRNA production or targeting or protein-RNA interactions. Can edit both viral and cellular RNAs and can edit RNAs at multiple sites (hyper-editing) or at specific sites (site-specific editing). Its cellular RNA substrates include: bladder cancer-associated protein (BLCAP), neurotransmitter receptors for glutamate (GRIA2 and GRIK2) and serotonin (HTR2C), GABA receptor (GABRA3) and potassium voltage-gated channel (KCNA1). Site-specific RNA editing of transcripts encoding these proteins results in amino acid substitutions which consequently alter their functional activities. Edits GRIA2 at both the Q/R and R/G sites efficiently but converts the adenosine in hotspot1 much less efficiently. Can exert a proviral effect towards human immunodeficiency virus type 1 (HIV-1) and enhances its replication via both an editing-dependent and editing-independent mechanism. The former involves editing of adenosines in the 5'UTR while the latter occurs via suppression of EIF2AK2/PKR activation and function. Can inhibit cell proliferation and migration and can stimulate exocytosis. [Isoform 1]: Has a lower catalytic activity than isoform 2. [Isoform 2]: Has a higher catalytic activity than isoform 1.
Synonyms: ADAR2; DRADA2; RED1; ADAR2g; DRABA2; hRED1; ADAR2a-L1; ADAR2a-L2; ADAR2a-L3; ADAR2a; ADAR2b; ADAR2c; ADAR2d; NEDHYMS
Tractability: Small molecule: it has a high-quality binding pocket. PROTAC: ubiquitination databases record sites on it; its protein half-life has been measured.
Target class: Enzyme; Hydrolase
Gene: Protein-coding gene on chromosome 21 (45,073,839 to 45,226,560, forward strand). Ensembl gene ENSG00000197381.
Subcellular location: Nucleus; Nucleus, nucleolus; Nucleus (Isoform 1); Nucleus (Isoform 2)
Subcellular location (Human Protein Atlas): Nucleoplasm; Cytosol
Pathways (Reactome):
Metabolism of RNA: C6 deamination of adenosine; Formation of editosomes by ADAR proteins
Gene Ontology:
Molecular function: double-stranded RNA adenosine deaminase activity; protein binding; RNA binding; double-stranded RNA binding; mRNA binding; adenosine deaminase activity
Biological process: adenosine to inosine editing; base conversion or substitution editing; mRNA modification; negative regulation of cell migration; negative regulation of cell population proliferation; negative regulation of protein kinase activity by regulation of protein phosphorylation; positive regulation of viral genome replication; regulation of cell cycle; RNA processing; mRNA processing
Cellular component: nucleolus; nucleoplasm; nucleus; cytoplasm
Genetic constraint (gnomAD): Loss-of-function variants: 10 observed, 52.57 expected, observed/expected ratio (o/e) 0.19, 90% interval 0.12 to 0.32. The upper end of that interval is the gene's LOEUF score, 0.32, which puts it in group 1 of 6, group 1 being the genes least tolerant of losing a copy. Missense variants: 638 observed, 953.88 expected, observed/expected ratio (o/e) 0.67, 90% interval 0.63 to 0.71. Synonymous variants: 348 observed, 388.59 expected, observed/expected ratio (o/e) 0.9, 90% interval 0.82 to 0.98.
Homologues: Orthologues: chimpanzee ADARB1 (99% identical), macaque ADARB1 (99% identical), mouse Adarb1 (95% identical), rabbit ADARB1 (95% identical), rat Adarb1 (94% identical), pig ADARB1 (91% identical), dog ADARB1 (84% identical), tropical clawed frog adarb1 (81% identical), guinea pig ADARB1 (80% identical), zebrafish adarb1b (78% identical), zebrafish adarb1a (72% identical), Drosophila melanogaster loqs (11% identical), and 4 more. Paralogues in human: ADARB2 (52% identical), ADAR (30% identical), ADAD1 (21% identical), ADAD2 (20% identical), ADAT1 (17% identical), STAU2 (14% identical), TARBP2 (12% identical), STRBP (11% identical), ILF3 (11% identical), STAU1 (11% identical), ZFR (11% identical), ZFR2 (10% identical), and 2 more.
Diseases named in the same sentence as ADARB1 in open-access papers:
ADARB1 is named in the same sentence as 53 diseases in open-access papers, as found by Europe PMC text mining. Sharing a sentence is not in itself a finding about the gene and the disease. The quoted sentences say what the papers report.
glioma (6 papers, 2019 to 2022). A benign or malignant brain and spinal cord tumor that arises from glial cells (astrocytes, oligodendrocytes, ependymal cells). "The ADARB1 alternative splicing variant (ASV) might be correlated with the invasiveness of gliomas." (PMID 31491024, 2019). "Surprisingly, we found that ADARB1 expression was significantly upregulated in TMZ-resistant glioma cells." (PMID 35177985, 2022). "In our study, we found the expression level of p-AKT significantly decreased in TMZ-resistant glioma cells after ADARB1 knockdown." (PMID 35177985, 2022). "We observed a positive correlation between IC50 values and ADARB1 expression in these glioma cells (Spearman r = 0.960, p = 0.009)." (PMID 35177985, 2022). "In glioma, aberrant expression of ADARB1 can affect the proliferation and invasion of glioma cells by regulating microRNAs or CDC14B-Skp2 signaling axis." (PMID 35004651, 2021). "Our study revealed RNA editing levels to be higher in control brain samples and it is significantly reduced in glioma samples which correlate with the RNA expression levels of the ADAR enzymes ADARB1 and ADARB2." (PMID 33062411, 2020). "Besides, a combined treatment with AKT inhibitor and ADARB1 knockdown obviously resulted in much slower proliferation rates of TMZ-resistant glioma cells, indicating that ADARB1 might be involved in AKT-mediated TMZ resistance of glioma cells." (PMID 35177985, 2022). "Furthermore, ADARB1 is found to be involved in AKT-mediated TMZ resistance in glioma cells." (PMID 35177985, 2022). "For example, the reported tumor-suppressive effects of ADAR2 (ADARB1) on glioma may contrast with our findings as a result of the differential binding of ADAR1 and ADARB1 on specific RNAs and modification sites on RNAs or effects on the larger tumor compartment." (PMID 35133980, 2022). "To further identify the effect of the ADARB1-mediated AKT signaling axis in TMZ-resistant GBM cells, we treated TMZ-resistant glioma cells with the AKT inhibitor MK2206." (PMID 35177985, 2022). "We also treated TMZ-resistant glioma cells with the combination of MK2206 and ADARB1 siRNA." (PMID 35177985, 2022). "Finally, we found that Adenosine deaminase RNA specific B1 (ADARB1, also known as ADAR2) was downregulated in gliomas other than grade 2 oligodendrogliomas, potentially contributing to the observed decrease in A-to-I editing and circular RNA formation." (PMID 35042936, 2022). "From this, we can say that overall RNA editing events occur at a reduced frequency in glioma compared to normal and ADAR family enzymes ADARB1 and ADARB2 may be responsible for this decreased editing." (PMID 33062411, 2020). "To further investigate whether ADARB1 expression is associated with the chemosensitivity of glioma cells, we used Spearman’s rank correlation method to examine the correlation between ADARB1 expression and TMZ sensitivity (IC50) in 5 glioma cell lines (U343, Hs683, U251, U118, and T98G)." (PMID 35177985, 2022). "Interestingly, we found reduced levels of ADARB1 and ADARB2 in glioma samples, indicating that these two ADAR family enzymes may play an important role in A-to-I RNA editing events in glioma." (PMID 33062411, 2020).
glioblastoma (5 papers, 2013 to 2025). The most malignant astrocytic tumor (WHO grade IV). "Other studies on glioblastoma multiforme and pediatric astrocytoma indicated that ADARB1 overexpression leads to decreased proliferation of U87 cells and decreased proliferation and migration of A172 and U118 cells." (PMID 32707902, 2020). "ADARB1, an editing mediating enzyme, has been detected at reduced RNA levels in brain tumors, and the overexpression of ADARB1 in a glioblastoma multiforme cell line has been shown to lead to decreased proliferation." (PMID 23135352, 2013). "Moreover, the ADARB1/miR-589-3p axis has been proven to inhibit glioblastoma cell migration and invasion." (PMID 31491024, 2019).
epilepsy (4 papers, 2015 to 2022). A brain disorder characterized by episodes of abnormally increased neuronal discharge resulting in transient episodes of sensory or motor neurological dysfunction, or psychic dysfunction. "The importance of this process is demonstrated by mice deficient in the RNA-editing enzyme ADARB1 which die approximately 20 days post-birth and show early onset epilepsy." (PMID 25916332, 2015). "Both ADAR1 and ADARB1 were elevated at the protein level in GSCs compared with NSCs and nonmalignant cells derived from epilepsy surgical resection specimens, but only ADAR1 was negatively associated with patient survival in all three GBM databases." (PMID 35133980, 2022).
developmental and epileptic encephalopathy (3 papers, 2021 to 2025). An epilepsy associated with developmental impairment that may be due to either the underlying etiology or the superimposed epileptic activity, or both. "ADARB1 is highly expressed in the brain and related to developmental and epileptic encephalopathy and psychiatric disorders." (PMID 40865610, 2025).
developmental delay (3 papers, 2021 to 2023). "Individual 12 had a homozygous likely pathogenic variant in ADARB1 (NM_015833.4:c.2165C > T, p.Ala722Val) that was associated with non-specific neuroimaging findings, seizures, and developmental delay." (PMID 38031187, 2023).
lung adenocarcinoma (3 papers, 2017 to 2020). A carcinoma that arises from the lung and is characterized by the presence of malignant glandular epithelial cells. "However, the specific function of ADARB1 in lung cancer, especially in lung adenocarcinoma (LUAD), is still not fully understood and requires further study." (PMID 31491024, 2019). "The expression level of ADARB1 in lung cancer cell lines is higher than that in normal human bronchial epithelial cells;higher mRNA expression level of ADARB1 predicts a better outcome in patients with lung adenocarcinoma." (PMID 28881680, 2017). "Additionally, adenosine deaminase RNA-specific B1 (ADARB1), a special type of ADAR, is expressed at low levels in H358 and A549 lung adenocarcinoma (LUAD) cells, which suggests that I might be a potential target in diagnostic and prognostic progression for patients with LUAD." (PMID 32303268, 2020).
lung carcinoma (3 papers, 2017 to 2021). "We further investigated the expression of ADARB1 in high- (95D) and low-metastatic (95C) human lung cancer cells." (PMID 31491024, 2019). "The down-regulation of ADARB1 may be related to the pathogenesis of non-small cell lung cancer, and low levels of ADARB1 in lung cancer are correlated with shorter first progression (FP), overall survival time (OS) and post-progression survival time (PPS)." (PMID 35004651, 2021). "Additionally, we knocked down the expression of ADARB1 by siRNA in Beas-2B and 95C lung cancer cells and found that ADARB1 was significant lower in siADARB1 compared to siNC cells." (PMID 31491024, 2019). "To investigate whether ADARB1 methylation levels is associated with metastasis of LUAD cells, we examined the expression of ADARB1 after DNMT inhibitors 5-aza-2-deoxycytidine (5-azaD) treatment in two lung cancer cell lines." (PMID 31491024, 2019).
brain tumors (2 papers, 2013 to 2020). "All 3 editing mediating enzymes, ADAR1 (ADAR), ADAR2 (ADARB1), and ADAR3 (ADARB2), is downregulated in brain tumors and ADARB2 is also negatively correlated with GBM grades." (PMID 32244981, 2020).
cervical cancer (2 papers, 2021). A primary or metastatic malignant neoplasm involving the cervix. "The result shows that POLR2J2, RBFOX3, RBMS1, ADARB1, AFF3, CSDC2 and CTIF were down-regulated in most of cervical cancer tissues compared with corresponding normal cervix tissues." (PMID 34863153, 2021).
depression (2 papers, 2022 to 2023). "Further supporting the role of adenosine in stress-induced depression, we also identified three adenosine deaminases (Ada, Adarb1, and Adarb2) in our CSDS and ASDS-CSDS-LSDS analyses." (PMID 37228107, 2023).
Epileptic encephalopathy (2 papers, 2021). A condition in which epileptiform abnormalities are believed to contribute to the progressive disturbance in cerebral function. "Our study further suggests that ADARB1 variants should be screened in DEE cases tested with ES and that ADARB1 should be included in the epileptic encephalopathies next-generation sequencing panels." (PMID 32719099, 2021). "Infants carrying bi-allelic variants of ADARB1, the gene encoding ADAR2, develop either epileptic encephalopathy or microcephaly associated with intellectual disability and seizures." (PMID 34681616, 2021).
Intellectual disability (2 papers, 2021 to 2025). "The common clinical manifestations of diseases caused by the ADARB1 gene variant include neurodevelopmental disorders, hypotonia, microcephaly, seizures, intellectual disability, and limb spasticity." (PMID 40217360, 2025).
ovarian carcinoma (2 papers, 2021 to 2023). A malignant neoplasm originating from the surface ovarian epithelium. "In ovarian cancer, the downregulation of ADARB1 has been reported to have a potential role in the development of ovarian cancer." (PMID 37547318, 2023). "However, the specific function of ADARB1 in ovarian cancer is still not fully understood." (PMID 35004651, 2021). "To further identify the function of ADARB1 in OC, we overexpressed of ADARB1 in HO8910pm and OVCAR3 ovarian cancer cells." (PMID 35004651, 2021).
schizophrenia (2 papers, 2015 to 2024). A major psychotic disorder characterized by abnormalities in the perception or expression of reality. "The marginally preserved turquoise module had 13 and 16 hub genes in CTS and SZP, respectively, with an overlap of only eight hubs, from which three were previously associated with schizophrenia: ADARB1, PNOC and XK." (PMID 25981335, 2015).
viral infection (2 papers, 2021). "Viral infection upregulated the expression level of an inosine writer, ADAR (also called ADAR1), observed in five out of six transcriptome experiments, while viral infection downregulated another inosine writer, ADARB1 (also called ADAR2), reported in one out of six experiments." (PMID 34502037, 2021).
colitis (1 paper, 2025). Inflammation of the colon. "Expression levels of Adarb1—encoding for ADAR2 that catalyzes Flna mRNA A-to-I deamination (Stulić and Jantsch, 2013)—did neither correlate with Flna expression nor editing levels and remained low but stably expressed during colitis." (PMID 40471139, 2025).
colorectal cancer (1 paper, 2019). A primary or metastatic malignant neoplasm that affects the colon or rectum. "In accordance with our findings, previous studies have demonstrated that the PKCζ/ADARB1 axis is a critical regulator of colorectal cancer metastases through regulating RNA editing mediated miR-200 secretion." (PMID 31491024, 2019).
conduct disorder (1 paper, 2024). A disorder diagnosed in childhood or adolescence age group characterized by aggressive behavior, deceitfulness, destruction of property or violation of rules that is persistent and repetitive, and within a one year period. "Notably, ADARB1 variants are associated with suicide attempt in patients with psychiatric disorders, and SLC25A24 relates to conduct disorder." (PMID 39020437, 2024).
esophageal squamous cell carcinoma (1 paper, 2019). Esophageal squamous cell carcinoma (ESCC) is a type of esophageal carcinoma (EC) that can affect any part of the esophagus, but is usually located in the upper or middle third. "A recent study has found that ADARB1 was positively associated with the editing level of SLC22A3, a metastasis suppressor in esophageal squamous cell carcinoma." (PMID 31491024, 2019). "By editing and stabilizing insulin-like growth factor binding protein 7 (IGFBP7), ADARB1 overexpression suppressed tumor growth and induced apoptosis in esophageal squamous cell carcinoma." (PMID 31491024, 2019).
Hypertension (1 paper, 2020). The presence of chronic increased pressure in the systemic arterial system. "To distinguish between these two possibilities, we examined the effect of hypertension in a double mutant mouse line in which the enzyme responsible for RNA editing of GluA2, ADAR2, has been knockout out (MMRRC; Adarb1:Gria2, here abbreviated GluA2R/R)." (PMID 32792936, 2020).
malignant pleural mesothelioma (1 paper, 2021). A malignant neoplasm that arises from mesothelial cells in the pleura and shows a diffuse growth pattern. "In addition, ADARB1-OE promotes cell growth, motility, and invasion of malignant pleural mesothelioma cells independent of its RNA-editing activity." (PMID 35004651, 2021).
mental disorder (1 paper, 2025). A disease that has its basis in the disruption of mental process. "Furthermore, some of these genes (e.g., NEGR1, PTBP2, BCL11A, ARNTL, SLC25A12, ADARB1) were identified in a recent study investigating the genetic overlap between AN and mental disorders, further supporting their relevance to AN." (PMID 39971893, 2025).
microcephaly (1 paper, 2021). A congenital or acquired developmental disorder in which the circumference of the head is smaller than normal for the person's age and sex. "Although this subject had profound DD, microcephaly and severe feeding difficulties, his electroclinical features were milder than all other known ADARB1 cases." (PMID 32719099, 2021). "In conclusion, we contribute to the delineation of ADARB1-related DEE phenotype, stressing the progressive course of this condition and the most relevant clinical aspects (profound DD/ID, progressive microcephaly and spastic tetraplegia and intractable epilepsy)." (PMID 32719099, 2021).
migraine (1 paper, 2015). "The gene is of potential interest with respect to migraine susceptibility as the glutamate and serotonin receptor gene RNAs are the predominant substrates modified by ADARB1 adenosine deamination." (PMID 25916332, 2015). "Considering the association of ADARB2 with migraine in the Norfolk Island pGWAS we decided to investigate SNPs in this gene, as well as another RNA editing gene, ADARB1, in an Australian migraine case–control population." (PMID 25916332, 2015). "The aim of this study was to determine if SNPs in the ADARB1 and ADARB2 genes contribute to migraine susceptibility in an Australian case–control cohort." (PMID 25916332, 2015). "In this study we tested four SNPs in the ADARB1 gene and eight SNPs in the ADARB2 for association with migraine susceptibility." (PMID 25916332, 2015). "The particular editing function of ADARB1 upon the AMPA glutamate receptor subunit (GRIA2) pre-mRNA makes the investigation of ADARB1 in migraine interesting, because glutamate is a major mediator in the CNS and its regulation has been studied as a possible mechanism causing migraine." (PMID 25916332, 2015). "The aim of this study was to investigate single nucleotide polymorphisms (SNPs) in the adenosine deaminase, RNA-specific, B1 (ADARB1) and adenosine deaminase, RNA specific, B2 (ADARB2) genes in an Australian case–control Caucasian population for association with migraine." (PMID 25916332, 2015). "In this study we genotyped four SNPs in ADARB1 and nine SNPs in ADARB2 using either TaqMan or Sequenom assays to investigate their involvement in migraine." (PMID 25916332, 2015).